TRIP13 (thyroid hormone receptor interactor 13)
Diseases named in the same sentence as TRIP13 in open-access papers (continued):
Sharing a sentence is not in itself a finding about the gene and the disease.
head and neck cancer (18 papers, 2017 to 2025). A primary or metastatic malignant neoplasm affecting the head and neck. "Overexpression of TRIP13 is associated with a poor prognosis for breast cancer, head and neck cancer, multiple myeloma, glioblastoma, and CRC." (PMID 33037736, 2020). "TRIP13 is responsible for the development of chemoresistance in head and neck cancer, but this gene may be linked with the drug resistance in BRCA." (PMID 31311202, 2019). "Furthermore, the high expression of TRIP13 has been associated with aggressive subtype, treatment resistance, and enhanced repair of DNA damage in head and neck cancer." (PMID 28157697, 2017). "Because it has been demonstrated that phosphorylation of TRIP13 at Y56 sensitizes head and neck cancer to the EGF receptor inhibitor cetuximab, we performed the clonogenic assay in all six cell lines, treated with or without cetuximab." (PMID 38216586, 2024). "In head and neck cancer, overexpressed TRIP13 interacts with the DNA-protein kinase C complex and activates the DNA repair process, thereby affecting drug resistance." (PMID 37627217, 2023). "In 2014, Banerjee and colleagues conducted a study examining the impact of TRIP13 on head and neck cancer development." (PMID 37740123, 2023). "There is increasing evidence that showed upregulated TRIP13 levels play a role in some tumors, including head and neck cancer, breast cancer, lung cancer, liver cancer, prostate cancer, gastric cancer, and human chronic lymphoblastic leukemia." (PMID 35075117, 2022). "TRIP13 was first reported as an oncogene in head and neck cancer, demonstrating an ability to promote tumour growth and enhance the repair of DNA damage." (PMID 35322916, 2022). "With that said, TRIP13 overexpression has been shown to promote a more aggressive state of growth in somatic head and neck cancer cells by activating double-stranded DNA repair through the NHEJ pathway." (PMID 34806647, 2021). "TRIP13 was first reported as an oncogene in 2014 in head and neck cancer, and several subsequent studies revealed that TRIP13 plays an oncogenic role in other neoplasms." (PMID 29540729, 2018). "Additionally, in a study investigating the protein–protein interactions of TRIP13 in head and neck cancer, suggesting a potential role in promoting tumor drug resistance via the nonhomologous end-joining (NHEJ) signaling pathway." (PMID 37740123, 2023). "TRIP13 was first reported as an oncogene of head and neck cancer in 2014, then other subsequent studies on cancers identified that TRIP13 might have oncogenic effects by promoting tumor cell proliferation, invasion, and metastasis." (PMID 35075117, 2022). "In addition, TRIP13 participated in the repair of chemotherapy resistance and cell transformation, further promoting the progression of head and neck cancer." (PMID 35517402, 2022). "Furthermore, TRIP13 fuels repair of chemoresistance of cancer cells and is involved in cellular transformation, leading to progression of head and neck cancers." (PMID 33037736, 2020). "Bannerjee and his colleagues first verified that TRIP13 is an oncogene and demonstrated that it induces chemoresistance in head and neck cancer by interacting with the DNA-PK complex to enhance non-homologous end joining." (PMID 31533816, 2019). "As the first research indicated that TRIP13 acts as an oncogene, Banerjee and his colleagues utilized mass spectrometry and Co-IP to explore how TRIP13 promotes head and neck cancer progression, and they found that TRIP13 promotes non-homologous end joining (NHEJ) and induces chemoresistance." (PMID 29540729, 2018). "In head and neck cancer, epidermal growth factor receptor (EGFR)-mediated phosphorylation of TRIP13 (pY56) enhanced non-homologous end-joining repair and induced radiation resistance in cancer cells." (PMID 38067275, 2023). "TRIP13 was reported to promote non-homologous end-joining repair (NHEJ repair) and induce chemoresistance in head and neck cancer." (PMID 35517402, 2022).
prostate carcinoma (18 papers, 2017 to 2026). A carcinoma that arises from epithelial cells of the prostate gland. "In prostate cancer, TRIP13 shows marked overexpression and is associated with unfavorable prognosis." (PMID 42099656, 2026). "TRIP13 promotes early steps of the DNA double-strand break repair and its presence was associated with progression in prostate cancer; and GINS1 plays a role in the initiation of DNA replication and has been part of a gene-set associated with outcome in early stage non-small cell lung cancer." (PMID 28968952, 2017). "We identified a significant upregulation of TRIP13 in proliferative tumor stem-like populations in prostate cancer." (PMID 42099656, 2026). "The elevation of TRIP13 in palbociclib resistant prostate cancer, together with the regulatory E2F1-TRIP13-HECTD3 axis, highlights its potential as a prognostic biomarker and therapeutic target." (PMID 42099656, 2026). "miR-515-5p was found to be downregulated in prostate cancer tissues, and TRIP13 was regulated directly by miR-515-5p." (PMID 38067275, 2023). "It has been reported that miR-515-5p serves as an inhibitor in prostate cancer by regulating TRIP13." (PMID 34774083, 2021). "For example, miR-515-5p directly targets the 3′-UTR of TRIP13 and negatively regulates its expression, thereby acting as a tumor suppressor in prostate cancer." (PMID 33413401, 2021). "TRIP13 expression in combination with preoperative PSA level was able to predict recurrence of prostate cancer." (PMID 28424416, 2017). "lncRNA TINCR suppresses the transcription and translation of TRIP13 in prostate cancer cells." (PMID 36157234, 2022). "Similarly, miR-515-5p dampens the proliferation and metastasis of prostate cancer by targeting TRIP13." (PMID 33413401, 2021). "However, in prostate cancer cells, miR‐515‐5p inhibits cell migration and invasion through targeting TRIP13 at its 3′‐UTR." (PMID 33037736, 2020). "Consistently, prostate cancer cells that acquired resistance to CDK4/6 inhibitors displayed marked TRIP13 overexpression, and functional assays revealed that TRIP13 modulates cellular sensitivity to these agents." (PMID 42099656, 2026). "One study found that TRIP13 promoted the proliferation, migration, and invasion and EMT of prostate cancer cells through regulation of tyrosine 3-monooxygenase/tryptophan 5-monooxygenase activation protein zeta (YWHAZ)." (PMID 36268276, 2022). "Although early studies reported that TRIP13 was a potential marker in lung cancer and prostate cancer, the direct link between TRIP13 and CLL has not been explored thoroughly." (PMID 28424416, 2017).
multiple myeloma (15 papers, 2012 to 2025). "Overexpression of Trip13 has been detected in many cancers and is associated with myeloma progression, disease relapse and poor prognosis inmultiple myeloma (MM)." (PMID 37942576, 2023). "These analyses reveal a CDK6-governed protein resistance signature that includes myeloma high-risk factors such as TRIP13 and RRM1." (PMID 35197447, 2022). "TRIP13 has also been implicated as a marker of early disease related mortality in multiple myeloma as part of a 70-gene model." (PMID 22075945, 2012). "Trip13 is a chromosomal instability gene in MM, which is related to drug resistance and disease relapse, and it has also been considered to be an important highly expression gene in a 70‐gene model of high‐risk myeloma by extensive gene expression profiling." (PMID 37942576, 2023). "Studies have found that TRIP13, as MRGs, constructs the prognostic characteristics of multiple myeloma and can be used as a prognostic marker for multiple myeloma." (PMID 41487520, 2025). "The role of TRIP13 in prostate, colorectal, lung, liver, and multiple myeloma has been identified, while its role in pancreatic cancer is not yet well defined." (PMID 38074464, 2023). "The overall survival of multiple myeloma patients was poor with elevated TRIP13 expression and aberrant TRIP13 expression in cancer cells leads to chromosomal recombination malformations." (PMID 38074464, 2023). "AAA-ATPase TRIP13 is one of the chromosome instability gene recently established in multiple myeloma (MM), the second most common and incurable hematological malignancy." (PMID 28157697, 2017). "Our results indicated that overexpression of TRIP13 led to decreased apoptosis and conferred protection against drug-induced cytotoxicity in myeloma cells when treated with increasing doses of Bortezomib (5–20 nM) (p < 0.05)." (PMID 28157697, 2017). "Meanwhile, the knockdown of TRIP13 inhibited myeloma cell growth, induced cell apoptosis, and reduced tumor burden in xenograft MM mice." (PMID 28157697, 2017). "Overexpressing human TRIP13 in myeloma cells prompted cell growth and drug resistance, and overexpressing murine TRIP13, which shares 93% sequence identity with human TRIP13, led to colony formation of NIH/3T3 fibroblasts in vitro and tumor formation in vivo." (PMID 28157697, 2017). "In addition, CD138+ cells from four patients with relapsed refractory myeloma and PBMCs from four healthy donors were collected, and the protein levels of TRIP13, YWHAE, and p-ERK were determined by performing immunoblotting." (PMID 38012658, 2023). "Furthermore, PI3K/Akt inhibition by LY294002 pretreatment partially restored cell sensitivity to Bortezomib in TRIP13-OE myeloma cells, although LY294002 alone had slightly inhibitive effects." (PMID 28157697, 2017). "TRIP13 could be used as a biomarker for the development and prognosis of multiple myeloma." (PMID 32903581, 2020). "Recently, an inhibitor specifically targeting TRIP13, DCZ0415, was developed and tested in myeloma experimental models and in primary cells derived from drug‐resistant myelomas." (PMID 35194944, 2022). "Overexpression of TRIP13 abrogated mitotic spindle checkpoint and induced proteasome-mediated degradation of MAD2 in multiple myeloma mainly through the Akt pathway." (PMID 32903581, 2020). "To evaluate the functional role of TRIP13 in myeloma pathogenesis, we overexpressed TRIP13 in the MM cell lines ARP1, OCI-MY5, and H929 using lentivirus-mediated human TRIP13-cDNA." (PMID 28157697, 2017). "Furthermore, this study showed that the treatment of immunocompetent myeloma models with DCZ0415 increases the numbers of immune cells (CD3, CD4 and CD8) and inhibits nuclear factor kappa B (NF‐κB) activity, suggesting the immunotherapeutic value of inhibiting TRIP13." (PMID 35194944, 2022).
multiple myeloma (continued). "Despite the fact that a Trip13‐specific inhibitor (DCZ0415) has been recently described, showing a potent antitumor activity in multiple myeloma in vitro and in vivo, it is not expected to be in the clinics any time soon." (PMID 36031387, 2022).
glioblastoma (11 papers, 2017 to 2025). The most malignant astrocytic tumor (WHO grade IV). "For example, TRIP13 is highly expressed in Glioblastoma and its inhibition impaired the proliferation, migration, and invasion of tumor cells by regulating c-MYC stability." (PMID 38464090, 2024). "The ATPase Thyroid hormone receptor interactor 13 (TRIP13), usually overexpressed in a myriad of human cancers, promotes glioblastoma migration and invasion by decreasing the transcription of FBXW7 and attenuating its inhibitory effects on c-MYC." (PMID 35515121, 2022). "The analysis showed that the recurrent samples (n = 16) exposed higher TRIP13 expression status than primary samples (n = 497) in the TCGA glioblastoma collective." (PMID 34066132, 2021). "In this study, TRIP13 methylation patterns are frequently altered in low-grade glioma and glioblastoma." (PMID 34066132, 2021). "Hence, the study was limited for TRIP13 expression analysis in primary glioblastoma to explore the relationship with IDH1." (PMID 34066132, 2021). "The analysis results showed that TRIP13 expression was significantly increased in glioblastoma." (PMID 34066132, 2021). "In addition, we investigated TRIP13 expression (by RNA-seq data) for specific tumor anatomic structure identified by H&E staining used Ivy Glioblastoma Atlas Project." (PMID 34066132, 2021). "Therefore, we utilized the GEO profile database to analyze the TRIP13 mRNA expression of glioblastoma stem-like (GS) cell lines, corresponding glioblastoma primary tumors and GS neurospheres in the GDS3885 dataset." (PMID 34066132, 2021). "Similarly, in glioblastoma, miR-92b targets FBXW7 and TRIP13 suppresses its transcription, thereby stabilizing oncogenic proteins like c−MYC and driving tumorigenesis." (PMID 40370434, 2025). "We previously reported that F-box/WD repeat-containing protein 7(FBXW7) suppressed the stemness and EMT of CCA, and a recent study proposed that FBXW7 expression was inhibited by TRIP13 in glioblastoma, so we further investigated the correlation between FBXW7 and TRIP13 in pCCA progression." (PMID 33648560, 2021).
lung carcinoma (11 papers, 2017 to 2025). "TRIP13 high expression is associated with poor prognosis of patients with liver, breast, gastric and lung cancer." (PMID 30564064, 2018). "A large number of studies suggested that TRIP13 gene is highly expressed in head and neck cancer, prostate cancer, lung cancer and breast cancer tissues and is closely associated with colorectal cancer, gastric cancer." (PMID 30564064, 2018). "Here, we demonstrate that melatonin (MT), a hormone synthesized in the pineal gland, downregulates the expression of TRIP13, particularly in lung cancer cells with high expression of TRIP13." (PMID 41145438, 2025). "Conversely, the proliferation, migration, and invasion abilities of lung cancer cells are significantly reduced when the expression of TRIP13 is inhibited." (PMID 40441196, 2025). "Among these targets, we have already analyzed three genes (FAM64A; miR-99a target, HELLs; miR-150-3p target, and TRIP13; miR-139-3p target) as oncogenic target molecules regulated by tumor-suppressive miRNAs in lung cancer." (PMID 39337462, 2024). "An important question is which molecular pathway is affected by the high expression of the TRIP13 gene in lung cancer cells." (PMID 38067275, 2023). "In lung cancer cells, TRIP13 knockdown inhibited malignant phenotypes, e.g., increased apoptosis, induced cell cycle arrest, and inhibited the proliferation, invasion, and migration abilities." (PMID 37627217, 2023). "Additionally, in vitro experiments also demonstrated that overexpression of TRIP13 promote lung cancer cell proliferation, migration, and invasion." (PMID 40441196, 2025). "Aberrant expression of TRIP13 has been reported in a wide range of cancers, including lung cancer." (PMID 38067275, 2023). "A study showed that TRIP13 is also related to the EMT pathway in lung cancer." (PMID 35907846, 2022). "Finally, the promoting effect of TRIP13 on lung cancer was verified, the results demonstrating TRIP13 could accelerate lung cancer cell proliferation, migration, and invasion." (PMID 40441196, 2025). "Moreover, The Cancer Genome Atlas (TCGA) data showed that TRIP13 is frequently mutated or amplified in several kinds of cancer such as lung cancer and esophagus cancer but not in CLL." (PMID 28424416, 2017). "Some of the predicted master regulators, including PTTG1, RFC4, TRIP13, BUB1B, TTK, and ZWINT are capable of promoting migration, invasion, and metastasis of lung cancer cells." (PMID 36304306, 2022).
bladder cancer (10 papers, 2020 to 2025). "Recently it has been shown that thyroid receptor-interacting protein 13 (TRIP13), a protein associated with the progression of several cancers, promotes proliferation and invasion of bladder cancer." (PMID 36197930, 2022). "In bladder cancer, overexpression of TRIP13 enhanced the resistance of cancer cells to cisplatin and doxorubicin." (PMID 38067275, 2023). "Epidermal growth factor was reported to activate the androgen receptor and increase the expression of TRIP13 to promote bladder cancer progression." (PMID 34374227, 2021). "Further, in bladder cancer cells, TRIP13 knockdown increases E‐cadherin and decreases N‐cadherin and Snail." (PMID 33037736, 2020). "Another study showed that with high expression of TRIP13, the expression of γH2A.X decreased and the expression of RAD50 increased in bladder cancer cells after cisplatin treatment, which revealed that TRIP13 promoted DSB repair and reduced apoptosis of cancer cells treated with drugs." (PMID 35601150, 2022). "In addition, previous studies have showed that TRIP13 induces platinum resistance in carcinoma, including head and neck squamous cell carcinoma and bladder cancer." (PMID 35601150, 2022). "In addition, TRIP13 promotes drug resistance, including head and neck squamous cell carcinoma and bladder cancer." (PMID 35601150, 2022). "Moreover, high expression of TRIP13 could lead to cisplatin and doxorubicin resistance in bladder cancer." (PMID 35601150, 2022).
liver cancer (9 papers, 2020 to 2025). An epithelial or non-epithelial malignant neoplasm that arises from the liver. "The increased expression of TRIP13 in liver cancer tissues is associated with liver cancer progression." (PMID 41179299, 2025). "High expression of thyroid hormone receptor interactor protein 13 (TRIP13) in liver cancer affects survival rate and is associated with enrichment of certain molecules in the processes of RNA degradation and fatty acid metabolism." (PMID 41179299, 2025). "Among these characteristic genes, DEPDC1, DEPDC1B, PRR11, and TRIP13 were risk factors for liver cancer patients." (PMID 36785674, 2023). "Meanwhile, DEPDC1, DEPDC1B, CALCRL, PRR11, and TRIP13 were significantly upregulated in liver cancer tissue, yet NGFR was downregulated." (PMID 36785674, 2023). "To further characterize the mechanisms involved in Trip13 KD effects in liver cancer cells, we focused on HLF cells as a representative human HCC cell line." (PMID 36031387, 2022). "The TRIP13 protein has been extensively studied in animal models, particularly in liver cancer." (PMID 37740123, 2023). "However, the present study reveals a new role of Trip13 in the regulation of lipid metabolism in liver cancer cells." (PMID 36031387, 2022). "Silencing TRIP13 could act as a tumor suppressor for liver cancer, which inhibited cell growth and metastasis in vivo and in vitro experiments." (PMID 32903581, 2020). "For example, thyroid hormone receptor-interacting agent A 13A (TRIP13) may act as a tumor promoter during the development of liver cancer." (PMID 33294448, 2020). "In liver cancer, the genes DEPDC1, DEPDC1B, PRR11, and TRIP13 have been explored in previous studies." (PMID 36785674, 2023). "Indeed, our findings now demonstrate that Trip13 regulates Akt activation, mainly mediated through the IR (a MIM containing protein), with Trip13 being a key player in the p31comet‐/Mad2‐dependent regulation of insulin signaling in liver cancer cells." (PMID 36031387, 2022).